EGF (epidermal growth factor)
Diseases named in the same sentence as EGF in open-access papers (continued):
Sharing a sentence is not in itself a finding about the gene and the disease.
renal carcinoma (6 papers, 2011 to 2021). A carcinoma arising from the epithelium of the renal parenchyma or the renal pelvis. "Most of these hub genes, except EGF, were upregulated DEGs, which were validated in 40 paired renal cancer and paracancerous tissues of Changzheng RCC database (supplementary)." (PMID 31950034, 2019). "Moreover, SIL treatment decreased the growth and invasiveness of renal cancer 786-O cell while restraining the growth of cell and inducing program cell death in cancer Caki-1 cells through prevention of EGF, ERK1/2." (PMID 34452574, 2021). "Epidermal growth factor (EGF) has been shown to stimulate the migration of breast, prostate and renal carcinoma cells." (PMID 21966417, 2011).
Thrombocytopenia (6 papers, 2009 to 2025). A reduction in the number of circulating thrombocytes. "One study reported significantly elevated EGF levels in dengue patients compared with healthy controls, but decreased EGF levels were associated with hypoalbuminemia and thrombocytopenia during the critical phase." (PMID 36297236, 2022). "Platelets are known to release several GFs (PDGF, EGF, TGF-β, FGF, etc.)during the repair of vascular injury or stimulation of inflammation, which could explain the decreased levels of PDGF and EGF in thrombocytopenia caused by dengue." (PMID 36297236, 2022). "Thrombocytopenia-associated changes common to both tumor types included an increase in RANTES, EGF, and angiopoietin-like 3 levels, and a reduction in PF4 levels." (PMID 38493157, 2024). "Studies have demonstrated decreased levels of platelet-derived growth factor (PDGF) and epidermal growth factor (EGF) in severe dengue compared with nonsevere dengue, which are associated with thrombocytopenia." (PMID 36297236, 2022). "These authors suggested that depletion of this growth factor might be due the thrombocytopenia since thrombocytes are an important source of EGF." (PMID 28586397, 2017). "Thrombocytopenia is a hallmark of DENV infection and since thrombocytes are an important source of RANTES and EGF, severe thrombocytopenia may explain the depletion of these two markers." (PMID 23717702, 2013). "Thus for EGF, thrombocytopenia can also reduce levels of circulating RANTES." (PMID 19156204, 2009).
urothelial carcinoma (6 papers, 2013 to 2022). A malignant neoplasm derived from the transitional epithelium of the urinary tract (urinary bladder, ureter, urethra, or renal pelvis). "Here, we report the generation and performance of a NIR-tagged ELP-epidermal growth factor (ELP-EGF) fusion protein to target overexpressed EGFR in urothelial carcinoma (also known as transitional cell carcinoma, TCC)." (PMID 36082359, 2022). "Recently it was shown in urothelial carcinoma cells that SH3BGRL3 can only indirectly interact with EGFR following stimulation of the cells with EGF for 10–30 min and that this interaction occurs through Grb2." (PMID 34380438, 2021). "Consistent with a role for FEME in EGFR signaling, the stable silencing of Endophilin increases phosphorylation of AKT, GSK3β, SFK and STAT3 after EGF stimulation, mimicking the signaling pattern in urothelial carcinoma." (PMID 32589750, 2020). "mTORCs pathway is important in urothelial carcinoma and it already known that EGF triggers mTORCs activation." (PMID 25596749, 2015). "In the present study, the critical role for Gab1 in EGF-mediated activation of mTORC pathways and the importance of Gab1 and mTORCs in urothelial carcinoma were investigated." (PMID 25596749, 2015). "Taken together, our results highlight the unique role of Gab1 in the regulation of mTORCs after EGF stimulation as well as the crucial role of Gab1 in urothelial carcinoma." (PMID 25596749, 2015). "Collectively, our results suggest that Gab1 is an essential regulator of the EGF-mediated mTORC pathways and may potentially be used as a biomarker for urothelial carcinoma to predict diagnosis and drug response." (PMID 25596749, 2015). "mTORCs (mammalian target of rapamycin complexes) and EGF are important in urothelial carcinoma." (PMID 25596749, 2015). "Therefore, Gab1 may play an important role in regulating EGF-mediated mTORC activity in urothelial carcinoma." (PMID 25596749, 2015). "Importantly, EGF plays a crucial role in urothelial carcinoma." (PMID 24023933, 2013). "EGF acts through EGFR to facilitate the development of various types of cancers, including urothelial carcinoma." (PMID 35013128, 2022).
allergic disease (5 papers, 2017 to 2025). An immune response that occurs following re-exposure to an innocuous antigen, and that requires the presence of existing antibodies against that antigen. "Recombinant human epidermal growth factor (rhEGF) has strict storage requirements and may trigger allergic reactions." (PMID 40590113, 2025). "Breast milk involves no risk of allergy, contains antibodies, epidermal growth factor (EGF), and erythropoietin, which may promote the growth and repair of skin cells." (PMID 31027386, 2019). "Our results indicated that lower proportions of NKT due to EGF and FGF21 supplementation at the end of the suckling period may be beneficial in the prevention of allergic diseases, which are highly prevalent during these stages of life." (PMID 32599899, 2020).
ameloblastoma (5 papers, 2016 to 2022). The most common odontogenic tumor, arising from the epithelial component of the embryonic tooth and usually affecting the molar-ramus region of the mandible or maxilla. "EGFR functions downstream of EGF and stimulates the migration and invasion of human ameloblastoma in an MMP-9 dependent mechanism." (PMID 29029486, 2017). "BA from periodontopathic bacteria does not directly affect the migration of ameloblastomas but has an indirect influence through the expression of epidermal growth factor (EGF) and transforming growth factor β1 (TGF-β1)." (PMID 35573798, 2022).
benign prostatic hyperplasia (5 papers, 1993 to 2022). A non-cancerous nodular enlargement of the prostate gland. "However, decreased EGF expression was found in elderly patients with benign prostate hyperplasia." (PMID 35886909, 2022).
bipolar disorder (5 papers, 2008 to 2026). A disorder of the brain that causes unusual shifts in mood, energy, activity levels and the ability to carry out day-to-day tasks. "This potential influence of EGF on novelty-seeking opens up a broader area of research and implications for the understanding of bipolar disorder." (PMID 40002454, 2025). "Furthermore, in a recent study conducted in young adult patients with MDD and bipolar disorder (BD), a significant disease-dependent increase in EGF serum levels was observed, suggesting that EGF may represent a potential biomarker for mood disorders." (PMID 41550142, 2026).
Cerebral ischemia (5 papers, 2015 to 2024). Restriction of arterial blood supply to the brain associated with insufficient oxygenation to support the metabolic requirements of the tissue. "In addition, epidermal growth factor (EGF) exerts neuroprotective effects on cerebral ischemia via activating the EGF receptor (EGFR), which also contributes to the activation of the PI3K/AKT/mTOR pathway and elevated HIF-1α." (PMID 33967696, 2021). "Neurotrophic factors may also contribute to the reduction of infarct volume in cerebral ischemia; vascular endothelial growth factor (VEGF), epidermal growth factor (EGF), bFGF, BDNF, and GDNF increase after MSC transplantation in rats." (PMID 26265166, 2015).
colon adenocarcinoma (5 papers, 2012 to 2022). "For instance, a study using pretreatment of Caco-2, a colon adenocarcinoma cell with EGF, showed a redistribution of TJPs, ZO-1, and occludin, while inhibition of MAPK/Erk has totally abolished the protective effects of EGF on tight junctions (TJs)." (PMID 35800225, 2022). "We were able to substantiate this observation by demonstrating that the presence of Grb3-3 reduced EGF-induced MAPK signalling indicated by pERK in the human colon adenocarcinoma Caco-2 cell line." (PMID 36171279, 2022). "Because EGF stimulation leads to cofilin activation in several cell lines, we tested colon adenocarcinoma cells treated with this growth factor." (PMID 22790341, 2012).
cystic kidney (5 papers, 2015 to 2025). "ORPK mouse models have also been employed to demonstrate the involvement of Na+/H+ exchanger (NHE) activation in epidermal growth factor (EGF)-induced renal cyst formation." (PMID 40076734, 2025). "EGF plays a pivotal role in renal development, renal cyst formation, and renal metabolism." (PMID 40076734, 2025). "In ORPK mouse models, EGF promotes the mitosis of collector duct cells by enhancing the exchange activity of NHE on the cell surface, thereby inducing renal cyst formation." (PMID 40076734, 2025). "Gene expression showed EGF down-regulation (-5.6-fold, FDR = 0.001) and MCP1 up-regulation (3.1-fold, FDR = 0.03) in PKD1 renal cysts compared to MCT." (PMID 36342644, 2023). "Indeed, we found a significant down-regulation of EGF and up-regulation of MCP1 in both human and murine PKD1 cystic kidney tissues from previously published microarray data, and confirmed this by qRT-PCR of additional cystic samples." (PMID 36342644, 2023). "Moreover, EGF mRNA levels decreased in cystic kidneys of an ADPKD murine model, while a number of growth factor genes increased with disease progression demonstrating an involvement of EGF with the progression of cystic lesions instead of ADPKD cystogenesis." (PMID 36342644, 2023). "Epidermal growth factor (EGF) is a small mitogenic protein involved in normal cellular proliferation, acceleration of fluid secretion, renal electrolyte homeostasis, and expansion of renal cysts." (PMID 31488014, 2019).
duodenal ulcer (5 papers, 2007 to 2025). An ulcer in the duodenal wall. "The growth factor, EGF accelerates gastroduodenal ulcer healing by stimulating cell migration and proliferation in epithelial cell monolayers, tissue repair, increasing release of gastric mucin, and attenuating gastric acid secretion." (PMID 18237397, 2008). "This indicates that EGF exerts a cyto-protective activity on gastric mucosa and, taken together with the evidence that EGF treatment determines levels of antral SLI significantly higher than that in control rats, proposes a role for EGF in preventing stress ulcer formation." (PMID 29149074, 2017).
emphysema (5 papers, 2013 to 2021). "Our findings of decreased levels of EGF in patients with emphysema are in line with this interesting bio-pathological pathway." (PMID 23577098, 2013). "Adjusted group comparisons revealed significant reductions in EGF (−0.317, p = 0.01), IL-15 (−0.21, p = 0.01), IL-8 (−0.180, p = 0.02) and IL-1ra (−0.220, p = 0.03) in subjects with emphysema and normal spirometry." (PMID 23577098, 2013). "Recent data from research performed in the homozygous mutant klotho (KL[−/−]) mouse suggest that increased apoptosis of airway cells via the inhibition of the EGF-dependent pathway may be involved in the development of the aging lung process that includes emphysema." (PMID 23577098, 2013). "Previous reports also supported that engrafted MSCs in the emphysema-secreted paracrine factors, such as VEGF, and EGF, to promote mechanism for the protective effects of pulmonary tissues from elastase injury." (PMID 32399043, 2020). "Regression coefficients showed that, compared to smokers without emphysema, subjects with emphysema had lower levels of EGF (−0.317, p = 0.01), IL-15 (−0.219, p = 0.01), IL-8 (−0.180, p = 0.02), and IL-1ra (−0.220, p = 0.03)." (PMID 23577098, 2013). "Similarly, a study conducted in smokers with computed tomography (CT) detected emphysema and without airway obstruction had demonstrated decreased plasma levels of cytokines including EGF, IL-8, IL-15, and IL-1RA than the smokers without CT detected emphysema." (PMID 25879453, 2015).
Erythema (5 papers, 2018 to 2025). Redness of the skin, caused by hyperemia of the capillaries in the lower layers of the skin. "Higher salivary EGF levels were statistically significantly associated with less severe erythema and ulceration." (PMID 41220465, 2025). "Treatment measures for adverse reactions included extending the cold compression time to 2 h for edema, erythema, and external application of human epidermal growth factor gel, which resulted in recovery 2 days later." (PMID 40729539, 2025). "In mice, both EGF and pimecrolimus—a topical calcineurin inhibitor—groups showed reduced erythema, inflammation, and expression of thymic stromal lymphopoietin (TSLP), a cytokine that plays a role in the pathogenesis of AD." (PMID 38202116, 2023). "In mice, both EGF and pimecrolimus groups showed less erythema with significantly reduced inflammation and decreased expression of thymic stromal lymphopoietin." (PMID 29862299, 2018).
esophageal squamous cell carcinoma (5 papers, 2014 to 2022). Esophageal squamous cell carcinoma (ESCC) is a type of esophageal carcinoma (EC) that can affect any part of the esophagus, but is usually located in the upper or middle third. "Kyse30 squamous cell esophageal carcinoma cells and FaDu squamous cell pharyngeal carcinoma were chosen to delineate effects of EpEX and EGF on EGFR signaling based on their responsiveness to EGFR-mediated EMT." (PMID 36076232, 2022). "Moreover, in esophageal squamous cell carcinoma, overexpression of the epidermal growth factor (EGF) increased specificity of protein 1 (Sp1) phosphorylation and activated the ERK1/2 pathway, thus enhancing FSCN1 expression." (PMID 34830909, 2021). "A recent study investigated the profiles of cytokines related to EGF and uPAR in 68 esophageal squamous cell carcinoma (ESCC) patients." (PMID 34729105, 2021).
glomerular diseases (5 papers, 2021 to 2025). "Urinary EGF is a biomarker for tubulo-interstitial damage and, as such, a hallmark of kidney disease progression, including deterioration of any glomerular disease." (PMID 34900856, 2021). "Higher levels of EGF are associated with better therapeutic response and disease remission in various glomerular diseases." (PMID 33974569, 2021). "Our results suggest that EGF may serve as a protective marker against podocyte injury in human glomerular diseases." (PMID 40713496, 2025). "Already in an early phase, tubulo-interstitial changes induced by glomerulopathies lead to diminished production and urinary excretion of epidermal growth factor (EGF), making urinary EGF a sensitive and ‘early stage’ biomarker for the deterioration of kidney function." (PMID 36996194, 2023). "There were significant diurnal variations in the concentrations of urinary PCR, ACR, NAG/Cr, and EGF/Cr across four periods over 24 h in pediatric patients with glomerular diseases, with a trough occurring during the overnight period and a peak occurring at a certain period during the daytime." (PMID 37300718, 2023). "It is reasonable to hypothesize that, compared to MCD, urinary EGF expression decreases more in FSGS, IgAN, and other glomerulopathies due to more pronounced glomerular damage and podocyte dropout." (PMID 34900856, 2021).
intrauterine growth restriction (5 papers, 2011 to 2020). "In human trophoblast, EGF has been shown to stimulate differentiation to SynT in vitro and decreased EGFR phosphorylation is associated with intrauterine growth restriction." (PMID 33141023, 2020). "In the third trimester placenta, THRs may have a general growth-promoting effect as they act through EGF, human placental lactogen or estradiol on trophoblast growth and differentiation, and their expression is reduced in pregnancies with fetal growth restriction and also lower placental weight." (PMID 32517091, 2020). "Nevertheless, growth factors such as EGF are believed to be intimately involved with the control of trophoblast physiology, and abnormal levels of EGFR have been reported in the placenta from pregnancies complicated by intrauterine growth restriction (IUGR), preeclampsia, and diabetes mellitus." (PMID 21876698, 2011).
invasive breast carcinoma (5 papers, 2011 to 2014). A carcinoma that infiltrates the breast parenchyma. "In an invasive breast cancer mouse model, macrophages have been implicated in assisting tumor cell motility by participating in an epidermal growth factor- (EGF-) CSF-1 paracrine loop where tumor cells secrete CSF-1 and macrophages contain the corresponding receptor and vice versa." (PMID 25054153, 2014). "EGF also increases the activity of LIMK in carcinoma cells and LIMK is upregulated in invasive mammary carcinomas." (PMID 23374291, 2013). "In conclusion, by applying various bioinformatical approaches we have revealed the decreased expression of pathway elements in the EGF signaling cascade and the decreased expression of the EGR1 gene on the mRNA level in the MDA-MB 231 human invasive breast carcinoma cell line." (PMID 23251236, 2013).
obstructive uropathy (5 papers, 2014 to 2024). "Studies of Nintedanib, alone or in combination with Gefitinib, an epidermal growth factor inhibitor, have shown beneficial effects on kidney fibrosis in experimental murine models of obstructive uropathy." (PMID 36430794, 2022). "These authors suggest that EGF is involved in the promotion of recovery from obstructive uropathy." (PMID 39240898, 2024). "The role of EGF was reported in obstructive uropathy, which could help in the recovery from tubular injury." (PMID 34682161, 2021).
Oral ulcer (5 papers, 2009 to 2023). Erosion of the mucous mebrane of the mouth with local excavation of the surface, resulting from the sloughing of inflammatory necrotic tissue. "As for epidermal growth factor, some researches showed that reduced epidermal growth factor may increase the proliferation of human fibroblasts and keratinocytes, resulting in a susceptibility to the development of oral ulcers." (PMID 30298136, 2018). "The search keywords included "recurrent aphthous stomatitis" OR "recurrent aphthous ulcers" OR "recurrent oral ulcers" AND "epidermal growth factor" OR "EGF" OR "VEGF" OR "vascular endothelial growth factor" AND "saliva" OR "salivary"." (PMID 37727361, 2023). "The EGF concentration in the saliva is decreased by RT, while the incidence of oral ulcer is increased in patients with low concentrations of EGF." (PMID 19456848, 2009). "They showed that levels of salivary EGF were lower in remission and active stages of RAS than in healthy individuals, indicating that salivary EGF levels were reduced even in the nonappearance of oral ulcers." (PMID 37727361, 2023). "It is well known that EGF and FGF2 play major roles in wound healing, and both have been used as regeneration factors in a diverse range of conditions, including burns, chronic wounds, oral ulcers, vascular ulcers, diabetic ulcers, pressure ulcers, and surgical incisions." (PMID 34306094, 2021).